CCDC39 (coiled-coil domain 39 molecular ruler complex subunit)
Description:
Required for assembly of dynein regulatory complex (DRC) and inner dynein arm (IDA) complexes, which are responsible for ciliary beat regulation, thereby playing a central role in motility in cilia and flagella. Probably acts together with CCDC40 to form a molecular ruler that determines the 96 nanometer (nm) repeat length and arrangements of components in cilia and flagella (By similarity). Not required for outer dynein arm complexes assembly.
Synonyms: DKFZp434A128; CILD14; FAP59; CFAP59
Tractability: Small molecule: a structure with a bound ligand is known. Antibody: its Gene Ontology location is reachable by antibodies, with medium confidence. PROTAC: ubiquitination databases record sites on it.
Gene: Protein-coding gene on chromosome 3 (180,602,858 to 180,684,942, reverse strand). Ensembl gene ENSG00000284862.
Subcellular location: Cytoplasm, cytoskeleton, cilium axoneme
Subcellular location (Human Protein Atlas): Acrosome; Basal body; Centrosome; Nucleoplasm
Gene Ontology:
Biological process: axonemal dynein complex assembly; cilium movement; cilium-dependent cell motility; determination of digestive tract left/right asymmetry; determination of liver left/right asymmetry; determination of pancreatic left/right asymmetry; epithelial cilium movement involved in determination of left/right asymmetry; flagellated sperm motility; heart looping; inner dynein arm assembly; lung development; motile cilium assembly; regulation of cilium beat frequency; cilium organization; protein localization to cilium
Cellular component: axoneme; cilium; motile cilium; cytosol; extracellular region
Genetic constraint (gnomAD): Loss-of-function variants: 58 observed, 58.85 expected, observed/expected ratio (o/e) 0.99, 90% interval 0.8 to 1.23. The upper end of that interval is the gene's LOEUF score, 1.23, which puts it in group 5 of 6, group 1 being the genes least tolerant of losing a copy. Missense variants: 653 observed, 659.74 expected, observed/expected ratio (o/e) 0.99, 90% interval 0.93 to 1.06. Synonymous variants: 225 observed, 221.01 expected, observed/expected ratio (o/e) 1.02, 90% interval 0.91 to 1.14.
Gene-disease validity (ClinGen):
ClinGen rates the evidence that CCDC39 causes each of these diseases.
primary ciliary dyskinesia 14 (autosomal recessive): Definitive.
Homologues: Orthologues: chimpanzee CCDC39 (99% identical), macaque CCDC39 (96% identical), pig CCDC39 (87% identical), dog CCDC39 (87% identical), rabbit CCDC39 (86% identical), rat Ccdc39 (77% identical), mouse Ccdc39 (75% identical), guinea pig CCDC39 (60% identical), tropical clawed frog ccdc39 (57% identical), zebrafish CCDC39 (43% identical), Drosophila melanogaster Ccdc39 (21% identical).
Diseases named in the same sentence as CCDC39 in open-access papers:
CCDC39 is named in the same sentence as 22 diseases in open-access papers, as found by Europe PMC text mining. Sharing a sentence is not in itself a finding about the gene and the disease. The quoted sentences say what the papers report.
primary ciliary dyskinesia (14 papers, 2015 to 2026). A rare, genetically heterogeneous, primarily respiratory disorder characterized by chronic upper and lower respiratory tract disease. "The aim of this study was to describe the sperm MMP and the ultrastructural abnormalities of the sperm flagella in a patient with Kartagener syndrome, whose genetic testing showed compound heterozygous mutations of the CCDC39 gene." (PMID 33005176, 2020). "In addition, we report, for the first time, the missense variant p.Arg811Cys in the CCDC39 gene in a patient with Kartagener syndrome." (PMID 33005176, 2020). "To this end, we acquired hABSCs bearing genetic mutations in the CCDC39 gene that cause primary ciliary dyskinesia (PCD), a disorder that can affect both the structure and function of cilia—in the case of the CCDC39 mutation, immotile cilia are produced." (PMID 40060463, 2025). "Disease-causing bi-allelic DNA variants in CCDC39 and CCDC40 are frequent causes of the hereditary disorder of primary ciliary dyskinesia (PCD)." (PMID 39056782, 2024). "Biallelic mutations of CCDC39 and CCDC40 have been found in patients with ‘radial spoke defects’ in primary ciliary dyskinesia." (PMID 37601242, 2023). "The mutants in Cfap59 (also known as Ccdc39) resulted in aberrant inner dynein arms and the dynein regulatory complex were identified in primary ciliary dyskinesia (PCD) patients." (PMID 31904090, 2020). "As such, our rat genetics data exclude the human heterozygous CCDC39 mutant allele and heterozygous L1CAM allele from the candidate genetic modifier elements that alter the disease severity of XLH and primary ciliary dyskinesia." (PMID 31771992, 2019). "Such structural alterations are also observed in the cilia of patients with PCD (primary ciliary dyskinesia) who have mutations in CCDC39 and CCDC40, the human orthologs of FAP59 and FAP172, respectively." (PMID 31319499, 2019). "CCDC39 and CCDC40 were first identified as causative mutations in primary ciliary dyskinesia patients; cilia from patients show disorganized microtubules, and they are missing both N-DRC and inner dynein arms proteins." (PMID 26348919, 2015). "Mutations in CCDC39 (e.g. c.1072del) and CCDC40 (e.g. c.901C>T) destabilize the radial spoke structure, leading to axonemal disorganization and loss of motility, as observed in primary ciliary dyskinesia (PCD)." (PMID 40847540, 2026). "CCDC39 and CCDC151 gene mutations reported in patients with primary ciliary dyskinesia." (PMID 33005176, 2020). "The key roles of CCDC39 and CCDC40, which are involved in axonemal disorganization and inner dynein arm loss, in patients with primary ciliary dyskinesia (PCD) have been demonstrated previously." (PMID 34508138, 2021). "The mutations in CCDC39 and CCDC40 are the major cause of primary ciliary dyskinesia with axonemal disorganization and absent inner dynein arms." (PMID 35233959, 2022).
Hydrocephalus (5 papers, 2012 to 2025). Hydrocephalus is an active distension of the ventricular system of the brain resulting from inadequate passage of CSF from its point of production within the cerebral ventricles to its point of absorption into the systemic circulation. "In conclusion, we report our successful generation of a novel rat model of neonatal hydrocephalus using CRISPR/Cas9 to introduce a recessive splice donor site mutation into the rat Ccdc39 gene." (PMID 31771992, 2019). "Deletion of the CCDC39 gene in KO mice causes neonatal hydrocephalus with abnormal motile cilia." (PMID 37900281, 2023). "The prh mutation identified within coiled-coil domain-containing 39 (Ccdc39) gene causes shorter and immotile ependymal cilia and impaired brain intraventricular CSF flow, which results in severe postnatal hydrocephalus phenotype within the first postnatal week." (PMID 37296418, 2023). "Interactions between L1cam and the ciliary morphology-related gene Ccdc39 were explored, with L1camy/- mutants in combination with Ccdc39prh/prh double mutants displaying more severe hydrocephalus, accelerating neonatal hydrocephalus development." (PMID 39908266, 2025). "Here, we studied the genetic interaction of two hydrocephalus-related genes, L1cam and Ccdc39, through genetic, survival and growth characterization of the Ccdc39prh/prh mutant rat in the presence and absence of an L1cam-null allele." (PMID 31771992, 2019). "Using CRISPR/Cas9 to model neonatal hydrocephalus in rats, we generated a Ccdc39 knockout line in Sprague Dawley rats." (PMID 31771992, 2019). "We previously discovered a gene mutation within the coiled-coil domain-containing 39 (Ccdc39) gene, which causes the progressive hydrocephalus (prh) phenotype in mice due to lack of ependymal-cilia-mediated cerebrospinal fluid (CSF) flow." (PMID 31771992, 2019).
male infertility (4 papers, 2022 to 2025). The inability of the male to effect fertilization of an ovum after a specified period of unprotected intercourse. "More recently, both genes were also associated to MMAF-related male infertility and the absence of CCDC39 was observed in CCDC39-mutant sperm flagella." (PMID 36873931, 2023). "Mutations in CCDC39, CCDC40, and CCDC103 presented cilia axonemal disorganization, absent inner dynein arms, and male infertility." (PMID 35955660, 2022).
Infertility (3 papers, 2022 to 2023). "We identified ten infertile male individuals with pathogenic variants in CCDC39 (one) and CCDC40 (two) encoding ruler proteins, RSPH1 (two) and RSPH9 (one) encoding radial spoke head proteins, and HYDIN (two) and SPEF2 (two) encoding CP-associated proteins, respectively." (PMID 36873931, 2023). "Furthermore, we found that the protein expression of CCDC39 was significantly decreased in sperm from the male proband (F2 II-1), who was diagnosed as having infertility due to MMAF." (PMID 35795318, 2022). "As one of more than 40 genes responsible for PCD, CCDC39-related PCD is inherited in an autosomal recessive pattern, and patients with CCDC39 variants commonly suffer from sinusitis, bronchitis, bronchiectasis, laterality defects, and infertility, among other conditions." (PMID 35795318, 2022).
Kartagener Syndrome (3 papers, 2020 to 2025). An autosomal recessive disorder characterized by a triad of DEXTROCARDIA; INFERTILITY; and SINUSITIS. "In this study, we identified a homozygous variant reported previously and two compound heterozygous variants of CCDC39 in two Chinese patients with PCD and Kartagener syndrome." (PMID 35795318, 2022). "Mutations of CCDC39 and CCDC151 genes have been reported in PCD/Kartagener syndrome patients only recently." (PMID 33005176, 2020). "We identified a homozygous variant reported previously and two compound heterozygous variants of CCDC39 possibly responsible for PCD pathogenesis, expanding the variant spectrum of Chinese PCD, Kartagener syndrome, and morphological abnormalities of the sperm flagella involving CCDC39." (PMID 35795318, 2022).
ciliopathies (2 papers, 2022 to 2023). "For example, ciliopathy patients with variants in CCDC39 or CCDC40 genes display severe derangement of the axoneme and especially poor patient outcomes, because the CCDC39 / CCDC40 complex is the “ruler” that sets the length for the repeating units of ODAs and IDAs12." (PMID 37781579, 2023). "Finally, several factors related to ciliopathies such as DNALI1, DNAAF1, CCDC65, CCDC39, and LRRC34 were strongly reduced already at P17 (14–31% of wild-type level)." (PMID 36611846, 2022).
cystic fibrosis (1 paper, 2015). Autosomal recessive disorder caused by pathogenic variants in the CFTR gene (cystic fibrosis transmembrane conductance regulator), which encodes a chloride and bicarbonate channel expressed in epithelial cells, and follow the diagnosis criteria. "Unexpectedly, the long-term prognosis of children with CCDC39 or CCDC40 mutations is worse than for other PCD patients, and similar to patients with cystic fibrosis." (PMID 26348919, 2015).
Insulin resistance (1 paper, 2021). Increased resistance towards insulin, that is, diminished effectiveness of insulin in reducing blood glucose levels. "In pig models, single nucleotide polymorphisms identified in the CCDC39 gene have been shown to be associated with body fatness, whereas reduced expression of the PDK gene (involved in glucose transport regulation by insulin) were observed in insulin-resistance obese subjects." (PMID 33975549, 2021).
Lung disease (1 paper, 2020). "Lung disease and lung function are reportedly worse in those with inner dynein arm and central apparatus defects with microtubular disorganization ultrastructural defects, most of whom have biallelic mutations in CCDC39 or CCDC40." (PMID 31960620, 2020).
respiratory infections (1 paper, 2024). "Defects of those proteins cause a stiff, rapid, and flickery ciliary beating pattern, recurrent respiratory infections, axonemal disorganization, and abnormal assembly of GAS8, CCDC39, and DNALI1." (PMID 39056782, 2024).
situs inversus (1 paper, 2020). A congenital condition in which there is complete right-to-left reversal of the position of the major thoracic and abdominal organs (that is, they are arranged in a mirror image of the normal positioning). "Accordingly, TEM analysis performed on respiratory cells from Old English Sheepdogs with situs inversus and respiratory symptoms revealed defective IDAs, nexin links, and radial spokes in CCDC39-deficient cilia." (PMID 33005176, 2020). "To date, few associations have been reported between mutations on the CCDC39 gene and situs inversus." (PMID 33005176, 2020).
CCDC39 also shares sentences with these, for which no sentence is quoted: papilloma (2 papers); bronchiectasis (1); bronchitis (1); endometritis (1); epilepsy (1); infection (1); Neonatal respiratory distress (1); schizophrenia (1); sinusitis (1); Situs inversus totalis (1); Ventriculomegaly (1).